CXCR3 (C-X-C motif chemokine receptor 3)
Diseases named in the same sentence as CXCR3 in open-access papers (continued):
Sharing a sentence is not in itself a finding about the gene and the disease.
lymphoma (continued). "Coexpression of PD-L1/PD-1 with CXCR3/CD36 in circulating lymphocytes and serum IL-19 levels contributes to poor prognosis and might be potential markers for extranodal involvement in lymphoma." (PMID 36726488, 2023). "The findings could also shed light on the role of circulating CXCR3 and CD36-positive lymphocyte cells in lymphoma." (PMID 36726488, 2023). "In conclusion, PD-L1/PD-1 coexpression with CXCR3/CD36 and serum IL-19 may be involved in lymphoma extranodal involvement and have prognostic and predictive values in lymphoma." (PMID 36726488, 2023). "PD-L1/PD-1 coexpression with CXCR3/CD36 in circulating lymphocytes was investigated in posttherapy lymphoma patients with extranodal involvement (n = 34) or without extranodal involvement (n = 44)." (PMID 36726488, 2023). "PD-L1/PD-1 coexpression with CXCR3/CD36 and IL-19 might play an inferior prognostic role in lymphoma, providing a new significant era in lymphoma immunotherapy, especially in patients with extranodal involvement." (PMID 36726488, 2023). "A few case reports described the presence of CXCL9 and CXCR3 17, as well as CXCL12 and CXCR4 18, on lymphoma cells and these CXC chemokines may serve as positive regulators for the lymphoma cells to aggregate in specific intravascular space." (PMID 24931821, 2014). "PD-L1/PD-1 coexpression with CXCR3/CD36 in peripheral lymphocytes has not been studied in lymphoma." (PMID 36726488, 2023). "In lymphoma patients without extranodal involvement, posttherapy PD-L1/PD-1 and CXCR3/CD36 coexpression were reduced, suggesting that chemotherapy might induce a disruption in PD-1/PD-L1 signaling." (PMID 36726488, 2023). "However, lymphoma patients without extranodal involvement had a lower posttherapy PDL-1/PD-1 coexpression with CXCR3/CD36 than in the pretherapy samples of the same patients." (PMID 36726488, 2023).
sarcoidosis (21 papers, 2005 to 2025). Sarcoidosis is a multisystemic disorder of unknown cause characterized by the formation of immune granulomas in involved organs. "TBX21, a Th1 cell transcription factor, can upregulate genes encoding IFN-γ and CXCR3 involved in sarcoidosis." (PMID 39904950, 2025). "It is worth mentioning that in the BALF derived from patients with sarcoidosis, an increase of ligands for CXCR3 and CCR6 (e.g., CXCL10 and CCL20, respectively) is seen." (PMID 41376646, 2025). "Compared to peripheral blood, T cells accumulated in the lungs of sarcoidosis patients exhibit upregulated expression levels of CXCR3, CCR5, IL-18R, and IL-12R, suggesting the translocation of Th1 cells from the bloodstream into the lungs." (PMID 39904950, 2025). "We noticed that, within CD45 RA–CCR7+ central memory Tregs, the frequency of CCR4+ CCR6+ CXCR3– Th17-like Tregs decreased in patients with sarcoidosis compared to the control group (26.65% (21.98; 32.04) vs. 32.59% (25.73; 38.39) with p < 0.01)." (PMID 37189479, 2023). "Next, we found increased levels of CXCR3-expressing Th1-like and Th17.1-like Treg cells in peripheral blood samples from patients with sarcoidosis, while CCR6-expressing Th17-like Tregs decreased." (PMID 37189479, 2023). "Next, we noticed that the relative number of CXCR3-expressing cells within EM Tregs were augmented in patients with sarcoidosis vs. the control group (46.47% (40.00; 55.01) vs. 34.53% (29.24; 38.97) with p < 0.01)." (PMID 37189479, 2023). "CXCR3-expressing Treg cell subsets—Th1-like CCR60078CXCR3+ Tregs and Th17.1-like CCR6+ CXCR3+ Tregs—significantly increased in patients with sarcoidosis vs. the control group (14.4% vs. 10.5% with p < 0.01 and 27.9% vs. 22.8% with p < 0.01, respectively)." (PMID 37189479, 2023). "Among T cells, we found increased levels of IL-2R+ TIGIT+ LAG3+ CD4+ T cells in IPF, increased levels of CXCR3+ CD226+ CD4+ T cells in sarcoidosis, and increased levels of PD1+ TIGIT+ CD57+ CD8+ T cells in CTD-ILDs." (PMID 36949950, 2023). "This is the first study to demonstrate the association of circulating imbalance Tfh cells, especially between CCR4− and CXCR3-expressing Tfh subsets in the development of sarcoidosis." (PMID 31974463, 2020). "This is the first study to demonstrate the association between the development of sarcoidosis and imbalance of circulating Tfh cells, especially CCR4− and CXCR3-expressing Tfh subsets." (PMID 31974463, 2020). "In blood, we observed Th17.0 (CCR6+CCR4+CXCR3−) cells with increased frequencies in sarcoidosis compared to health." (PMID 32774332, 2020). "Similar to sarcoidosis CXCL10 is significantly elevated in CVID-ILD derived BALF being one of the main chemokines attracting not only CXCR3 positive TH1 cells but also CD21lowT-bethi B cells which likewise express high levels of this chemokine receptor." (PMID 33613543, 2020). "The past years have seen the emergence of Th1 mediators such as CXCR3/CXCR3 ligands (interferon gamma regulated CXC chemokines) as factors leading to granuloma formation, the pathogenetic hallmark of sarcoidosis." (PMID 23181555, 2012). "BAL lymphocytes in sarcoidosis are reported to be highly positive for the Th1-specific chemokine receptor CXCR3." (PMID 22513006, 2012). "We have also detected that an increase, however, does not reach statistical significance (P = .06) at mRNA levels of CXCR3 in IPF in comparison with sarcoidosis' patients." (PMID 20169144, 2009). "We showed increased levels of CXCR3+ CD226+ CD4+ T cells in sarcoidosis." (PMID 36949950, 2023). "To test this, we used flow cytometry to compare the T-bet-expressing frequencies in peripheral blood Th17.0 (RORγt+CCR6+CCR4+CXCR3−) cells between sarcoidosis subjects with different clinical trajectories defined by longitudinal changes in lung function and immunosuppression use." (PMID 32774332, 2020).
sarcoidosis (continued). "In addition, significantly more lymphocytes expressing TH1-associated receptors CXCR3, CCR5, IL-12R, and IL-18R were observed in sarcoid BAL fluid compared to peripheral blood of sarcoidosis patients, indicating translocation of TH1 cells from blood into the lungs." (PMID 33036432, 2020). "Increased levels of MIG and CXCR3 were demonstrated in biopsy and BAL fluid samples of patients with sarcoidosis, which is correlated with the number of CD4+ and total lymphocytes." (PMID 38611622, 2024). "One recent study by Ragusa in 2018 has reported high levels of Th1 dependent chemokines, MIG, CXCL9, and CXCR3 positive alveolar macrophages in BAL and biopsy samples of sarcoidosis patients." (PMID 38611622, 2024). "CXCR3− CCR6− Tfh2 and CXCR3− CCR6+ Tfh17 cells increased, while CXCR3+ CCR6− Tfh1 and CXCR3+ CCR6+ CCR4− Tfh17.1-like cells decreased in sarcoidosis patients." (PMID 33036432, 2020). "A CXCR3+CCR6+ Th subpopulation that rivals with Th1 in INFγ production has been recently described as Th17.1 and identified in sarcoidosis and Crohn’s disease." (PMID 28289412, 2017). "In regressing sarcoidosis, relationships were observed between T-bet and IL2RB, IL15RA, CXCR3, IL2, and IFNG." (PMID 26696750, 2015). "Among chemokine receptors, mRNA expressions of CCR2-var.A (P = 0.018), CCR5 (P = 0.003), CXCR3 (P < 0.001), and CXCR6 (P < 0.001) were elevated in sarcoidosis patients." (PMID 26696750, 2015). "The close relationships in sarcoidosis as a whole were found between T-bet and IL2RB, IL15RA, and CXCR3, which was related to CXCR6 and IFNG." (PMID 26696750, 2015). "We and other authors have previously shown that CXCR3/CXCL10 interaction is involved in the pathogenesis of other Th1-mediated processes, such as Crohn's disease and sarcoidosis." (PMID 15743470, 2005). "We also noted a statistically significant increase in central memory CXCR5+CCR6–CXCR3– follicular Th cells, as wells as effector memory CXCR5+CCR6–CXCR3– and CXCR5+CCR6+CXCR3– follicular Th cells in both groups of patients with sarcoidosis vs. healthy controls." (PMID 41376646, 2025). "Using mass cytometry analysis of immune cell subsets in bronchoalveolar lavage fluid (BALF), the analysis of T and B cells revealed increased levels of CXCR3+ CD226+ CD4+ T cells and the presence of FCRL5+ B cells in sarcoidosis patients with advanced lung lesions." (PMID 39896815, 2024). "Cluster #5508, prevalent in sarcoidosis, was characterized by CD4+ CD226+ CXCR3+." (PMID 36949950, 2023). "We speculate that CD4 T cells migrating to the lungs through CXCR3 may be activated through CD226, potentially contributing to the pathogenesis of sarcoidosis." (PMID 36949950, 2023). "Indeed, we showed that sarcoidosis patient’s CD45 RA–CCR7– effector memory Tregs were able to migrate to peripheral inflamed tissues from the bloodstream, expressed high levels of CXCR3, and were enriched with Th1-like and Th17.1-like Tregs." (PMID 37189479, 2023). "In contrast, additional phenotyping of CD4+CD45RA- memory T cells demonstrated an expansion of CXCR5-expressing T follicular helper (TFH)-like cells with a significant increase of CXCR3-expressing TFH1-like cells and a decrease of CCR6-expressing TFH17-like cells when compared to sarcoidosis." (PMID 33613543, 2020). "Our correlation analysis revealed relationship of T-bet and sarcoid inflammation, namely, its association with key sarcoidosis-associated cytokine IFNG, and receptors IL2RB, IL15RA, CXCR3, and CXCR6, regardless of the disease outcome." (PMID 26696750, 2015). "Induction of CXCR3 with CXCL9 and/or CXCL10 allows for T cell migration into organ tissues, including those that are typically thought of as immune privileged, and contributes to Th1 cell differentiation, which are common features of sarcoidosis." (PMID 24199653, 2013). "BAL lymphocytes in sarcoidosis have been reported to be highly positive for CCR5 and CXCR3." (PMID 20169144, 2009).
sarcoidosis (continued). "Increase in CXCR3 CD226 CD4 in sarcoidosis • CXCL9 and CXCL11 are ligands of CXCR3, are IFN-inducible and found in granulomas.• CXCR3 expressing CD4+ T cells are recruited in granuloma.B cells: more prevalent in the BAL of sarcoidosis and CTD-ILD patients compared to IPF." (PMID 39896815, 2024). "Furthermore, we found that Treg cells had a ‘proinflammatory’ phenotype, since CXCR3-expressing Treg cell subsets, including CCR6-CXCR3+ Th1-like and CCR6 + CXCR3+ Th17.1-like Treg cells, were elevated in peripheral blood samples from patients with sarcoidosis compared to healthy controls." (PMID 39598118, 2024).
tuberculosis (21 papers, 2005 to 2025). A chronic, recurrent infection caused by the bacterium Mycobacterium tuberculosis. "Since the CXCR3/ligand axis is associated with Th1-cell-mediated immunity, a previous history of tuberculosis and other chronic diseases may potentially influence the blood levels of IFN-γ-inducible chemokines." (PMID 34501934, 2021). "The beneficial effect of CXCR3 mutation on the control of mycobacterial infection in the zebrafish host should drive further research into the CXCR3-CXCL11 axis as a potential target for host-directed therapy against tuberculosis." (PMID 25573892, 2015). "In this study, patients with active tuberculosis had high levels of cIP-10 and a reduced frequency of CXCR3+ T cells was observed at the pulmonal site of infection compared to peripheral blood." (PMID 30507970, 2018). "In future work it will therefore be of great interest to investigate how macrophage and T-cell responses determined by CXCR3 signaling cooperate in the control of mycobacterial infections, using adult zebrafish or mammalian models of tuberculosis." (PMID 25573892, 2015). "In this study, the authors used a zebrafish model of tuberculosis to investigate the role of CXCR3 in macrophages during the early stages of mycobacterial infection." (PMID 25573892, 2015). "Together, the studies in mice and zebrafish models support further investigation of the CXCR3 signaling axis as a host therapeutic target for tuberculosis." (PMID 25573892, 2015). "Upregulation of CXCR3 in vaccine-induced T cells with potential to home to lung mucosa in tuberculosis suggests that these CD8 T cells described herein could play a role in the protection against severe respiratory diseases such as SARS-CoV-2." (PMID 36380764, 2022). "Prevention of mycobacterial dissemination by targeting the CXCR3 pathway, therefore, might represent a host-directed therapeutic strategy for treatment of tuberculosis." (PMID 25573892, 2015). "However, in an animal model of tuberculosis, there is differential expression of these chemokine receptors in T-lymphocytes isolated from different lung compartments and most cells were both CXCR3+ and CCR5+." (PMID 21829471, 2011). "Interestingly, the CXCL10/CXCR3 interaction played an important role in tuberculosis." (PMID 24732949, 2014). "To assess the potential contribution of different ‘polarized’ CD8+ T cell subsets in tuberculosis pathogenesis, we further analyzed the peripheral blood CD8+ T cells for inflammatory subsets classified by CCR6 and CXCR3 co-expression." (PMID 37761328, 2023). "Active tuberculosis in SCC increases the expression of CD3 (46.4±24.8 vs. 24.0±16.0, p<0.05), CXCR3 (35.1±16.4 vs. 19.2±13.3, p<0.01) and IP-10 (63.5±21.9 vs. 35.5±21.0, p<0.01), while expression of FOXP3 is decreased (3.5±0.5 vs. 13.3±3.7 p<0.05, p<0.05)." (PMID 22438899, 2012). "Moreover, a number of biomarkers, such as IFN-γ, CXCR3, CXCL9, CXCL10, and a combination of miRNAs, have demonstrated notable significance in the diagnosis of subclinical tuberculosis (STB)." (PMID 39274240, 2024). "Similarly, CXCR3+CD8+ T cells were depleted from the circulation in TB, and this CD8+ T cell subset slightly and progressively recovered by the end of the anti-tuberculosis therapy." (PMID 37761328, 2023). "CXCL10 is upregulated in the human lung during active TB, recruiting CD4+ T cells to the lungs via CXCR3 during M. tuberculosis infection." (PMID 37896952, 2023). "CXCR3 antagonism via truncated CXCL10 may also be an important regulatory mechanism occurring in tumors and in sites of tuberculosis (TB) pathology." (PMID 37896834, 2023).
type 1 diabetes (21 papers, 2014 to 2026). "Of interest, elevated frequency of peripheral blood CD8+ NK cells with homing marker CXCR3 is associated with an increased risk for Type 1 diabetes, a T-cell mediated autoimmune condition." (PMID 39085199, 2024). "We conclude that the CXCR3 response in antigen-experienced B cells is dysregulated during the progression of type 1 diabetes." (PMID 41273416, 2026). "Both CXCR3 and its ligands have a key role in the pathogenesis of type 1 diabetes, playing a fundamental role in the recruitment of T cells to pancreatic islets." (PMID 41273416, 2026). "Previously, we observed a reduction of CXCR3 expression on memory B cells from donors with type 1 diabetes, predominantly in individuals with a diagnosis for more than 3 years." (PMID 41273416, 2026). "We observed reduced CXCR3 expression on antigen-experienced B cells in individuals with a long duration of type 1 diabetes, although B cells remained responsive to IFNγ." (PMID 41273416, 2026). "CXCR3 expression is limited in CD20+ B cells in pancreases from recent-onset individuals diagnosed with type 1 diabetes under 7 years of age, but evident on CD8+ T cells that express CD20." (PMID 41273416, 2026). "We first confirmed our previous observations of a reduced expression of CXCR3 on B cell subsets, specifically in donors with LD type 1 diabetes." (PMID 41273416, 2026). "CXCR3 expression has been detected on infiltrating islet CD3+ T cells in the pancreas of individuals with RO type 1 diabetes, with both studies including adult-onset individuals." (PMID 41273416, 2026). "Together, our data show that, while CXCR3 is highly expressed in the pancreas of donors with RO type 1 diabetes who were diagnosed at <7 years of age, the expression is restricted to CD8+ T cells that co-express CD20." (PMID 41273416, 2026). "In donors with RO type 1 diabetes, B cells are more responsive in culture and readily upregulate CXCR3 and CD95, compared with ND individuals." (PMID 41273416, 2026). "In conclusion, our study demonstrated that combination of the CXCR3 antagonist ACT-777991 with aCD3 treatment resulted in synergistic diabetes remission in two preclinical models of type 1 diabetes." (PMID 37458220, 2023). "CXCL10 and its cognate receptor CXCR3 have been previously identified as potential therapeutic targets in type 1 diabetes, orchestrating the migration of islet-specific T cells into the pancreas." (PMID 37458220, 2023). "Combining anti-CD3 treatment with the blockade of the CXCR3/CXCL10 axis using ACT-777991, a CXCR3 antagonist, further preserves B-cell damage and synergistically increases persistent remission in experimental models of type 1 diabetes." (PMID 37458220, 2023). "Specifically, CXCR3 was shown to be increased on various T-cell subsets in patients with type 1 diabetes, including naïve and EM CD8+ T-cells and follicular T helper cells." (PMID 37458220, 2023). "CXCR3 is increased on various T-cell subsets in patients with type 1 diabetes, including effector memory CD8+ T cells." (PMID 37458220, 2023). "In animal models of type 1 diabetes, pancreatic insulitis was associated with CXCL10 production and inhibition of the CXCL10/CXCR3 axis prevented development of autoimmune diabetes." (PMID 36059840, 2022). "Expression of C-X-C motif chemokine receptor 3 (CXCR3) is reduced on CD3+ T cells in individuals with long-standing type 1 diabetes." (PMID 32157332, 2020). "The antigen-specific cells in individuals with type 1 diabetes expressed increased CXCR3 and decreased CCR7, indicating differentiation to Th1-like effector cells." (PMID 32157332, 2020). "A disease-linked phenotype was detected in individuals with long-standing type 1 diabetes, characterised by reduced C-X-C motif chemokine receptor 3 (CXCR3) expression on switched (CD27+IgD−) and unswitched (CD27intermediateIgD+) memory B cells." (PMID 29881878, 2018).